OR6B3 (olfactory receptor family 6 subfamily B member 3)
Description:
Odorant receptor.
Synonyms: OR6B3P; OR6B3Q
Tractability: Antibody: its Gene Ontology location is reachable by antibodies, with high confidence; UniProt places it where antibodies can reach, with medium confidence; UniProt predicts a signal peptide or a membrane-spanning region; the Human Protein Atlas places it where antibodies can reach.
Gene: Protein-coding gene on chromosome 2 (240,044,571 to 240,053,807, reverse strand). Ensembl gene ENSG00000178586.
Subcellular location: Cell membrane
Subcellular location (Human Protein Atlas): Plasma membrane; Cytosol
Pathways (Reactome):
Sensory Perception: Expression and translocation of olfactory receptors
Gene Ontology:
Molecular function: odorant binding; olfactory receptor activity; G protein-coupled receptor activity
Biological process: sensory perception of smell; detection of chemical stimulus involved in sensory perception of smell; G protein-coupled receptor signaling pathway
Cellular component: plasma membrane; membrane
Genetic constraint (gnomAD): Loss-of-function variants: 1 observed, 0.35 expected, observed/expected ratio (o/e) 2.85. That is too few expected variants to judge how well the gene tolerates losing a copy. Missense variants: 247 observed, 294.88 expected, observed/expected ratio (o/e) 0.84, 90% interval 0.75 to 0.93. Synonymous variants: 118 observed, 128.91 expected, observed/expected ratio (o/e) 0.92, 90% interval 0.79 to 1.07.
Homologues: Orthologues: macaque OR6B3 (88% identical), mouse Or6b3 (82% identical), rat Or6b3 (82% identical), mouse Or6b2 (79% identical), mouse Or6b2b (79% identical), rat Or6b2b (79% identical), dog OR6B2 (78% identical), dog OR6B2D (76% identical), dog OR6B2C (76% identical). Paralogues in human: OR6B2 (89% identical), OR6P1 (51% identical), OR6Q1 (45% identical), OR5A2 (44% identical), OR8I2 (44% identical), OR5A1 (43% identical), OR8D4 (43% identical), OR8U1 (43% identical), OR5AS1 (43% identical), OR11L1 (42% identical), OR5AP2 (42% identical), OR8H1 (42% identical), and 84 more.